STAT3 (signal transducer and activator of transcription 3)
Diseases named in the same sentence as STAT3 in open-access papers (continued):
Sharing a sentence is not in itself a finding about the gene and the disease.
liver fibrosis (continued). "SOCS3, by virtue of its function of STAT3 signalling suppressor may also provide an anti-fibrotic contribution, as STAT3 promotes liver fibrosis, and increased gene expression of the anti-fibrotic fibronectin type III domain containing 5 (Fndc5, also known as irisin) was observed in the KD group." (PMID 35995402, 2022). "Moreover, TGFβ can directly activate the JAK1/STAT3 axis in HSCs to induce liver fibrosis." (PMID 35517817, 2022). "Therefore, we further validated whether the JAK1/STAT3 signaling pathway was involved in the LS-mediated anti-liver-fibrosis process." (PMID 35517817, 2022). "Therefore, it was concluded that AHWE could restrain the activation of HSCs through the suppression of the STAT3 signaling pathway, which ultimately mitigated liver fibrosis." (PMID 36588728, 2022). "Additionally, IL-6/STAT3 signaling has been correlated with liver fibrosis and HSC activation." (PMID 32085494, 2020). "Therefore, we speculated that fructose‐induced up‐regulation of p‐STAT3 may transfer into the nucleus to recruit on ZEB1 promoter, causing ZEB1 nuclear translocation in rat liver fibrosis." (PMID 33058500, 2020). "Because the neutralization of IL-17A restored autophagy activity and attenuated the hepatic fibrosis, and IL-17A inhibited autophagy by phosphorylating STAT3, we examined whether inhibiting autophagy by activating STAT3 could reverse the antifibrotic effect of IL-17A-neutralizing Ab." (PMID 28039485, 2017). "Preclinical studies have shown that these exosomes can attenuate liver fibrosis by inhibiting activation of HSCs, regulating macrophage polarization, and suppressing profibrotic signaling pathways like Hedgehog/SMO and STAT3." (PMID 41487942, 2026). "Our study confirms the critical role of THBS1 in RILI and identifies it as a mediator of hepatic fibrosis in RILI through PDGF/PDGFR and JAK2/STAT3 signaling pathways." (PMID 41394148, 2025). "In both in vitro and in vivo liver fibrosis model, it suppresses HSC activation by inhibiting TGF-β1/Smad3 pathway thus reduces α-SMA and collagen I expression as well as targets JAK2/STAT3 pathway to regulate cell proliferation and apoptosis." (PMID 41293246, 2025). "Our study shows a significantly higher p-STAT3/p-STAT1 ratio in the liver fibrosis group, which further increases with anti-IFNAR blockade, suggesting STAT3’s role in mitigating fibrosis." (PMID 40260261, 2025). "Further investigation showed that PZH ameliorates liver fibrosis by modulating key targets, including AKT1, EGFR, and STAT3." (PMID 41181146, 2025). "In a CCl4-induced liver fibrosis model, Que-BMSC-EVs inhibited M1-type macrophage polarization and alleviated liver inflammation by suppressing the GNAS/PI3K/ERK/STAT3 signaling pathway." (PMID 40852596, 2025). "The recent identification of PZH’s modulation of the EGFR/JAK1/STAT3 pathway enhances its known inhibitory effects on the TGF-β1/Smad2 axis, thereby elucidating a multifaceted mechanism against hepatic fibrosis." (PMID 41181146, 2025). "To further verify the therapeutic effect of Ssb1 on liver fibrosis by STAT3 inhibition, we utilized a thioacetamide (TAA)‐induced liver fibrosis model to estimate the antifibrosis effect of Ssb1." (PMID 41163803, 2025). "PZW alleviated hepatic fibrosis in vivo, primarily by inhibiting collagen accumulation through navigating IL-6/JAK2/STAT3 and TGF-β/Smad2/3 signaling pathways." (PMID 41293246, 2025). "DHM enhances IFN-γ expression through the NF-κB/STAT3 pathway to improve NK cell killing, inhibits HSCs activation and significantly improves the CCL4-induced liver fibrosis." (PMID 40761743, 2025). "Our previous study demonstrated that MSCs-derived exosomes exert protective effects against liver fibrosis by delivering miR-148a to macrophages, which targets the KLF6/STAT3 pathway." (PMID 40873954, 2025).
liver fibrosis (continued). "In a CCl4-induced mouse model of liver fibrosis, ASP promoted IL-22 secretion, inhibited HSCs activation, and effectively attenuates fibrosis through the IL-22/STAT3 pathway." (PMID 39995661, 2025). "At the 7.5 mg/kg dose, NIC significantly enhanced the expression of SIRT-1, AMPK, PGC1-α, PPARγ, and STAT3 by 2.43-, 2.56-, 3.14-, 1.76-, and 1.90-fold, respectively, compared to the TAA-induced liver fibrosis group, and reduced HIF-1α expression by 28.23%." (PMID 41365955, 2025). "In liver fibrosis, HSPB1 activates JAK2/STAT3 and TGF-β1/Smad pathways, while it regulates cell proliferation and directly interacts with JAK2/STAT5 in myelofibrosis." (PMID 39863585, 2025). "Reduction of STAT3 levels, Inhibition of ECM deposition, and improving liver function in mice with liver fibrosis, presenting a promising anti-fibrotic therapeutic approach." (PMID 39494266, 2024). "This study investigated the anti-fibrotic and anti-inflammatory effects of STAT3 decoy oligodeoxynucleotides (ODN) in hepatocytes and liver fibrosis mouse models." (PMID 38338338, 2024). "This study aimed to investigate the anti-fibrotic and anti-inflammatory effects of STAT3 decoy ODN in hepatocytes and liver fibrosis mouse models." (PMID 38338338, 2024). "STAT3 is a JAK signal transducer and is closely related to the occurrence and development of liver fibrosis." (PMID 39338294, 2024). "In fibroblasts and fibrotic diseases, such as systemic sclerosis and CCl4-induced liver fibrosis, another SMAD-independent TGF-β1 activation pathway has been described that activates JAK2 and STAT3." (PMID 39060930, 2024). "IL-6 through its receptors of IL-6R (CD236) and glycoprotein 130 can activate the Janus kinases (JAK) and signal transducer and activator of transcription 3 (STAT3) signaling, enhancing liver fibrosis." (PMID 37679346, 2023). "S-allyl-cysteine (one of the major antioxidants in aged garlic extracts) attenuates CCl4-induced hepatic fibrosis in rats, with mechanisms of action related to reduced SMAD3 and phosphorylation of STAT3." (PMID 36671504, 2023). "In mouse models of liver fibrosis, sorafenib ameliorates liver fibrosis by activating SHP-1 and inhibiting STAT3 to promote apoptosis of hepatic stellate cells." (PMID 37291088, 2023). "TGFβ1, a STAT3 target gene, promotes liver fibrosis by increasing the expression of TGF-β1 in a liver fibrosis mouse model and a rapid early STAT3 activation was observed in HSCs and fibroblasts, but not in normal hepatocytes." (PMID 37978263, 2023). "Treatment of dihydromyricetin (DHM) can inhibit HSC activation in vitro and decrease CCl4-induced liver fibrosis in C57BL/6 mice by improving NK cell killing ability and IFN-γ expression through the NF-κB/STAT3 pathway." (PMID 37239062, 2023). "Triggering IL6/STAT3 signaling enhances HSC activation and liver fibrosis, while IFNγ/STAT1 signaling exhibits opposite effects." (PMID 37860111, 2023). "Both STAT3 and AKT2 have been reported in the literature to be closely related to liver fibrosis, and inhibiting STAT3 or AKT2 can treat liver fibrosis." (PMID 35517817, 2022). "Targeting STAT3 in HSCs by using exosomes to carry the Stat3-ASO significantly reduces the level of STAT3 mRNA, thereby inhibiting the activation of HSCs and thus improving liver fibrosis." (PMID 36569303, 2022). "Here, lycorine was able to diminish STAT3 activation, as evidenced by decreasing the phospho-STAT3 (Tyr-705) expression induced by TAA in hepatic tissue, which in turn protected against liver fibrosis." (PMID 35337166, 2022). "For instance, STAT3 dimerization inhibitor “STX-0119” is suggested to play a role in controlling the development of CCl4 and TAA-induced liver fibrosis through lessening the activated HSCs." (PMID 35337166, 2022). "Qu et al73 found that exosomes containing miR‐181‐5p increased autophagy and alleviated TGF‐β 1‐induced liver fibrosis by inhibiting the STAT3/Bcl‐2/Beclin‐1 pathway in HST cells and CCl4‐induced liver fibrosis in mice." (PMID 33506641, 2021).
liver fibrosis (continued). "A PPI network showed that as hub and core targets, SRC, PIK3R1, STAT3 and AKT1 were potential anti-liver fibrosis targets of RGGs." (PMID 35115923, 2021). "BM-MSCs transplantation also alleviated CCl4-induced rat liver fibrosis by suppressing the levels of IL-17A accompanied by the downregulation of the IL6/signal transducer and activator of transcription 3 (STAT3) signaling pathway." (PMID 34680522, 2021). "Meanwhile, much evidence has confirmed that PIK3R1, STAT3 and AKT1 can regulate crucial cellular processes, including proliferation, survival, growth, autophagy, and metabolism, and improve liver fibrosis." (PMID 35115923, 2021). "Our results collectively suggest that PSS prevents hepatic fibrosis by suppressing inflammation, promoting ECM decomposition and inactivating HSCs through the TGF‐β1/Smad2/3 and JAK2/STAT3 pathways." (PMID 32233073, 2020). "In view of the finding that autophagic death plays a significant role in progression of hepatic fibrosis, we examined the potential impact of the JAK2/STAT3 pathway on regulation of cellular autophagy." (PMID 32233073, 2020). "STAT3 can be activated by TGF-β1 treatment both in a SMAD-dependent and -independent manner, and it is known as a key therapeutic target in hepatic fibrosis." (PMID 33261209, 2020). "In the current study, we elucidated the hepatoprotective effect of SMSP administration in DEN-induced hepatic fibrosis and HCC in a rat model, likely through suppression of the TGF-β/STAT3 signaling pathway." (PMID 32121064, 2020). "TGF-β1, a well-known pivotal cytokine in the development of hepatic fibrosis, clearly contributes to HSC activation and activates the signal transducer and activator of transcription 3 (STAT3) signaling." (PMID 33261209, 2020). "Interestingly, studies have also revealed antioncogenic roles of STAT3 in RAS-dependent HCC and early-stage HCC developed from carbon tetrachloride (CCl4)-induced liver fibrosis, implying that specific genetic context and etiology of the disease may impact the outcome of STAT3-targeted therapeutics." (PMID 31731457, 2019). "A small-molecule STAT3 inhibitor (C188-9) alleviated EndMT in cultured cells and bile duct ligation (BDL) induced liver fibrosis in mice." (PMID 31776330, 2019). "Anti-fibrotic effects of C7A were evaluated in a thioacetamide (TAA)-induced liver fibrosis model, which indicated that C7A significantly inhibited ECM deposition through inhibiting STAT3 signaling." (PMID 31861943, 2019). "Activation of STAT3 in HSCs can help promote HSC survival, proliferation, and activation, thus promoting the formation of hepatic fibrosis." (PMID 29795016, 2018). "Plumbagin inhibits liver fibrosis by decreasing the expression of epidermal growth factor receptor (EGFR) and transcription factor 3 (STAT3) in the liver." (PMID 28770223, 2017). "We have demonstrated that exosomes containing miR‐181‐5p can increase autophagy and reduce TGF‐β1‐induced liver fibrosis by inhibiting the STAT3/Bcl‐2/Beclin 1 pathway in HST cells and a CCl4‐induced liver fibrosis mouse model." (PMID 28382720, 2017). "Our study suggests that the IL-17A/STAT3 signaling pathway plays a crucial role in the pathogenesis of hepatic fibrosis through suppressing hepatocellular autophagy and that blocking this pathway may provide therapeutic benefits for the treatment of hepatic fibrosis." (PMID 28039485, 2017). "In conclusion, our results demonstrate that IL-22/STAT3 regulates HSC activation and ameliorates liver fibrosis through modulating expression of miR-200a and β-catenin." (PMID 27819314, 2016). "Several studies have demonstrated an important role of STAT5 in liver fibrosis and cancer development through TGF-beta and STAT3 activation." (PMID 21464922, 2011). "Overall, the antifibrosis determination in animals showed that Ssb1 could reduce the indices of liver fibrosis in the TAA and CCl4‐induced models and regulate STAT3 phosphorylation and p‐STAT3/Gli1 interaction in fibrotic livers." (PMID 41163803, 2025).
liver fibrosis (continued). "Molecular biology verified that THBS1 could mediate hepatic fibrosis by participating in the activation of the PDGF/PDGFR signaling pathway, followed by the activation of the JAK2/STAT3 signaling pathway, ultimately mediating liver fibrogenesis." (PMID 41394148, 2025). "IL-22 exerts anti-inflammatory effects by polarizing KCs to M2 phenotype via activation of the signal transducer and activator of transcription 3 (STAT3) pathway and suppression of extracellular-regulated kinase 1/2 (ERK1/2) and Akt pathways in CCl4-induced liver fibrosis." (PMID 41479922, 2025). "Additionally, in the hepatic fibrosis mouse model, fibrotic liver tissues exhibited marked upregulation of EGFR, p-JAK1/JAK1, and p-STAT3/STAT3 protein expression (P < 0.01), accompanied by increased phosphorylation of JAK1 and STAT3 (P < 0.01)." (PMID 41181146, 2025). "Of which, core targets (EGFR, STAT3, JAK1) all are enriched in cancer signaling pathways, given their high connectivity in the PPI network and established crosstalk in liver fibrosis, we hypothesized that PZH modulates the EGFR/JAK1/STAT3 signaling axis." (PMID 41181146, 2025). "Whether PPARγ, HIF-1, STAT3, or other unrevealed transcription factors are involved in the induction of GPR81 in liver fibrosis is worthy of further investigation." (PMID 38982366, 2024). "For instance, a recent study showed that TGF-β could promote liver fibrosis by directly activating Janus kinase 1 (JAK1) and signal transducer and activator of transcription 3 (STAT3), with the assistance of the SMAD signaling pathways." (PMID 38766485, 2024). "Since STAT3, NFκB, and PPARγ are closely related to the pathology of NASH and liver fibrosis, we hypothesized that XYS may exert antifibrotic effects through these three TFs." (PMID 39338294, 2024). "miR-148a, which is enriched in MSC-derived EVs, can target KLF6 to reprogram the proinflammatory phenotype of macrophages to the anti-inflammatory phenotype by inhibiting the signal transducer and activator of transcription 3 (STAT3) pathway and consequently can alleviate liver fibrosis." (PMID 39099892, 2024). "However, the increased expression of serum EBI3 can promote the high expression of gp130 in HSCs, activating the JAK1/STAT3 pathway, which in turn inhibits the expression of ECM and leads to attenuated liver fibrosis." (PMID 37480105, 2023). "Mechanistically, we showed that accumulation of liver fibrosis-related cytokines, including TGFβ, IFNγ, TNFα, etc, could induce UC-MSC senescence and SASP through activation of JAK/STAT3 signaling pathway." (PMID 37507381, 2023). "Our results suggested that LS could exert anti-liver-fibrosis effects by inhibiting the activation of HSCs, targeting JAK1 and STAT3, and regulating the JAK1/STAT3 signaling pathway." (PMID 35517817, 2022). "Therefore, STAT3 and JAK1 are potential target proteins in HSCs for the treatment of liver fibrosis." (PMID 35517817, 2022). "HSC-based in vitro experiments demonstrated that LS could inhibit the cell viability, promote the cell apoptosis, decrease the expression of liver fibrosis markers, as well as downregulate the JAK1/STAT3 signaling pathway." (PMID 35517817, 2022). "In addition, Th17 cells also have obvious effects on liver fibrosis, and the possible mechanism is that IL-17 directly acts on hepatic stellate cells in a JNK- and STAT3-dependent manner to induce collagen production." (PMID 35935983, 2022). "The results showed that LS could inhibit the cell viability, promote the cell apoptosis, decrease the expression of liver fibrosis markers, and downregulate the JAK1/STAT3 signaling pathway." (PMID 35517817, 2022). "In vitro studies then demonstrated that LS could inhibit the HSC viability, promote the HSC apoptosis, decrease the expression of liver fibrosis markers, and downregulate the JAK1/STAT3 signaling pathway." (PMID 35517817, 2022).
liver fibrosis (continued). "Comparative analysis with HCV-infected and DAA-cured human liver chimeric mice highlighted an HCV-specific viral footprint, since these mice do not develop liver fibrosis, which also involves the STAT3 phosphatase PTPRD." (PMID 33801181, 2021). "For example, absence of SOCS3 leads to the liver fibrosis by increasing the production of TGF-β that was mediated by STAT3." (PMID 34784837, 2021). "Hence, we thought that RGGs presented anti-liver fibrosis activity by regulating the expression of SRC, PIK3R1, STAT3, AKT1 and other core targets." (PMID 35115923, 2021). "In conclusion, PSS prevents hepatic fibrosis by suppressing inflammation, promoting extracellular matrix (ECM) decomposition and inactivating hepatic stellate cells through mechanisms involving the TGF‐β1/Smad2/3 and JAK2/STAT3 pathways in vivo and in vitro." (PMID 32233073, 2020). "In addition, ERK/Akt/Stat3, a downstream pathway of PDGF related to liver fibrosis, was inhibited by byakangelicin." (PMID 32643868, 2020). "The protective effect of Src inhibition against liver fibrosis was associated with the attenuation of TGF-β-induced phospho-Smad3 expression, but not with the attenuation of STAT3 phosphorylation." (PMID 32120837, 2020). "Moreover, the STAT3 pathway is involved in the ADSC exosome-induced autophagy and reduction of TGF-β1-induced hepatic fibrosis." (PMID 32190672, 2020). "In addition, it has been reported that Asiatic acid can ameliorate CCl4-induced liver fibrosis in rats by regulating PI3K/AKT/mTOR, Bcl-2/Bax, Nrf2/ARE, NF-κB/IκBα and JAK1/STAT3 signaling pathways." (PMID 31467589, 2019). "The activation of hepatic stellate cells by IL6/STAT3 to promote liver fibrosis has been documented in F. hepatica infection in humans and mice which is in line with our findings in terms of the activation status of the IL6 and STAT3 signaling pathways at W14." (PMID 31555289, 2019). "This might be justified by the fact that TGFβ is crucial in the development of liver fibrosis, as previous data proposed that upon development of liver fibrosis, TGFβ traps STAT5 in hepatocytes and lead to the activation of STAT3." (PMID 30346985, 2018). "Treg cytokine IL-10, which has been coupled with the activation of JAK-STAT1 or STAT3 signaling cascade and found high expression in liver fibrotic tissues, was used to reverse therapeutic effect of IL-17A antibody in TAA-induced hepatic fibrosis mice." (PMID 28039485, 2017). "STAT3 activation accompanies enhanced phospho-Smad3 and CTGF expression in liver fibrosis." (PMID 29152065, 2017). "In conclusion, plumbagin could ameliorate the development of hepatic fibrosis through its downregulation of EGFR and STAT3 in the liver, especially in hepatic stellate cells." (PMID 26550019, 2015). "Blockade of STAT3 signaling pathway could attenuate liver fibrosis, revealing negative correlation between STAT3 activation and the degree of liver injury." (PMID 41394148, 2025). "A previous study reported that STAT3 directly participated in the activation and transdifferentiation of HSC in response to TGFβ and subsequent hepatic fibrosis, it also showed that the JAK1/STAT3 signaling pathway played an important role in HSC activation and liver fibrosis." (PMID 35517817, 2022). "A study of HBV-induced liver fibrosis, cirrhosis and HCC in mouse model, the DTNA/STAT3 signaling pathway can be activated and in turn further activates the STAT3 signaling pathway, stimulating expression of TGF-1, thus promoting the progression of HBV-induced liver fibrosis, cirrhosis, and HCC." (PMID 34976809, 2021). "Moreover, HCV-induced STAT3 signaling also triggers the upregulation and secretion of the metalloprotease MMP-2, which is involved in remodeling the extracellular matrix and has been previously suggested as a prognostic marker for liver fibrosis." (PMID 33801181, 2021).